TTR (transthyretin)
Diseases named in the same sentence as TTR in open-access papers (continued):
Sharing a sentence is not in itself a finding about the gene and the disease.
mood disorder (1 paper, 2015). A cognitive disorder a disturbance in which the person's mood is hypothesized to be the main underlying feature. "Taken together, RBP-4/TTR complex, thyroxine and vitamin A are all present in the CSF and participate in brain maturation and, cognitive, acquisition of memory and behavioral activities and may be implicated in mood disorders." (PMID 26645624, 2015).
motor polyneuropathy (1 paper, 2024). "After clinical and neurophysiological evaluation, seven patients (21%) had evidence of sensory–motor polyneuropathy and were started on treatment, whereas 26 presymptomatic carriers of TTR mutation began regular follow‐up." (PMID 37725003, 2024).
mucinous colorectal adenocarcinoma (1 paper, 2023). "and proteins involved in ECM organization, including DDR1, LAMA5, and TTR, were upregulated in mucinous colorectal adenocarcinoma." (PMID 37158593, 2023).
mucinous tumors (1 paper, 2019). "Similarly, apolipoprotein A1 has been detected in conjunction with transthyretin and transferrin in low grade mucinous tumors." (PMID 31315664, 2019).
muscle atrophy (1 paper, 2019). The loss of muscle tissue due to inactivity or disease. "The goal of these agents is to reduce the buildup of the transthyretin protein, for which accumulation of abnormal transthyretin deposits leads to muscle atrophy, reduced pain sensations, and reduced mobility in the body, which are ultimately responsible for causing disease." (PMID 31540086, 2019).
Myalgia (1 paper, 2023). "TTR has also been described in microdialysis samples from muscle tissue in patients chronic myalgia." (PMID 37420193, 2023).
myelodysplastic syndrome (1 paper, 2023). A clonal hematopoietic disorder characterized by dysplasia and ineffective hematopoiesis in one or more of the hematopoietic cell lines. "This study aims to investigate the prognostic significance of transthyretin in newly diagnosed myelodysplastic syndromes (MDS)." (PMID 36960201, 2023).
myeloid leukemia (1 paper, 2017). A clonal proliferation of myeloid cells and their precursors in the bone marrow, peripheral blood, and spleen. "There is, however, no direct evidence in the literature showing the association of myeloid leukemia (either CML or AML) with differential abundance of TTR and/or CD5L." (PMID 28117336, 2017).
Myotonia (1 paper, 2023). An involuntary and painless delay in the relaxation of skeletal muscle following contraction or electrical stimulation. "Induction of myotonia (wild-type mice + 9-AC + DMSO) was established as a mean of >13 s TTR after 10 min of intraperitoneal 9-AC treatment." (PMID 37372969, 2023). "After 9-AC administration (n = 7–9 mice), we measured the induced myotonia by quantifying the repositioning reflex time (TRR), i.e., the time it takes a mouse to roll over on all four legs after being placed in a supine position (mean of 0.5 s TTR before 9-AC treatment)." (PMID 37372969, 2023).
non-communicating hydrocephalus (1 paper, 2022). "This regression was confirmed at the functional level since TTR immunoreaction was also found to be scarce or absent in the frontal and middle part of the SCO in non-communicating hydrocephalus." (PMID 36553409, 2022).
Noonan syndrome with multiple lentigines (1 paper, 2023). A rare multisystem genetic disorder characterized by lentigines, hypertrophic cardiomyopathy, short stature, pectus deformity, and dysmorphic facial features. "This is also the case for 8/14 syndromic HCM (CACNA1C, FLNC, PRKAG2, PTPN11 (Noonan), PTPN11 (Noonan syndrome with multiple lentigines), RAF1, RIT1, TTR), 3/12 DCM (DES, TNNC1 and TNNT2), and 2/6 ARVC (JUP, TMEM43) gene-disease pairs." (PMID 37872640, 2023).
oesophageal cancer (1 paper, 2010). "Although at present SAA, transthyretin and apolipoprotein A-1 as individual markers may be too non-specific to influence therapeutic decisions, taken together, these plasma proteins may represent a panel of circulating markers that provide information about response to therapy in oesophageal cancer." (PMID 20551956, 2010).
papilloma (1 paper, 2020). A benign epithelial neoplasm that projects above the surrounding epithelial surface and consists of villous or arborescent outgrowths of fibrovascular stroma. "Moreover, expression of several proteins such as S-100, cytokeratin, vimentin and transthyretin (TTR) favors a CP papilloma diagnosis." (PMID 32375819, 2020).
Peripheral arterial occlusive disease (1 paper, 2022). "Peripheral arterial occlusive disease (PAOD) is one of the primary manifestations of systemic atherosclerosis, and transthyretin and complement factor B are potential markers for monitoring plasma PAOD disease." (PMID 36358920, 2022).
placental insufficiency (1 paper, 2017). Failure of the placenta to deliver an adequate supply of nutrients and oxygen to the fetus. "Understanding of how microRNAs control biogenesis of TTR, a key molecule in regulating fetal growth, will help us to uncover the underlying causes of placental insufficiency and IUGR." (PMID 29185488, 2017).
primary congenital glaucoma (1 paper, 2022). "Significantly lower levels of TTR and RBP3 were measured in the aqueous humor of primary congenital glaucoma patients." (PMID 35682657, 2022).
rectal cancer (1 paper, 2013). A primary or metastatic malignant neoplasm that affects the rectum. "In the multivariate analysis, tumor localization was significantly associated with OS and TTR, where rectal cancers exhibited a poorer prognosis." (PMID 24144331, 2013).
rectal tumors (1 paper, 2013). "Tumor localization was significantly associated with both OS and TTR in the multivariate analysis where patients with rectal tumors exhibited a poorer prognosis." (PMID 24144331, 2013).
Senile plaques (1 paper, 2020). Senile plaques are extracellular deposits of amyloid in the gray matter of the brain. "Additionally, TTR levels in the CSF are negatively correlated with disease severity and abundance of senile plaques, and TTR levels in plasma negatively correlate with disease stage." (PMID 32197355, 2020).
Splenomegaly (1 paper, 2022). Abnormal increased size of the spleen. "The other four groups (CB, CB-PolyA, CB-hFIX, and TTR-PolyA) had at least one mouse with visible splenomegaly upon sacrifice, indicated also by weights over 0.100 g." (PMID 36507314, 2022). "Encouragingly, TTR-hFIX mice exhibited the least collagenous area, even lower than the controls, at endpoint of all groups and no splenomegaly, suggesting this rAAV8 vector did not cause a detrimental collagen deposition response in these mice and was safe." (PMID 36507314, 2022).
synovitis (1 paper, 2017). Inflammation of a synovial membrane. "This study is the first to show that transgenic overexpression of TTR led to deposition on cartilage and increased the severity of cartilage damage and synovitis in the surgically induced murine OA model." (PMID 28941045, 2017).
cancer (64 papers, 2005 to 2026). A tumor composed of atypical neoplastic, often pleomorphic cells that invade other tissues. "The severity of the cancer associated catabolism as well as the inflammation status affect serum TTR and RBP levels." (PMID 16225703, 2005). "For instance, TTR is associated with cancer and its presence in ascitic fluid." (PMID 40836974, 2024). "A previous study also showed decreased protein expression of aryl sulfotransferase, enoyl-CoA hydratase, and transthyretin in the liver of rats under restraint stress, suggesting that cancer susceptibility could be enhanced by CRS." (PMID 28293639, 2017). "For example, TTR has been shown to interact directly with cancer cells and signalling pathways to regulate the tumour microenvironment, including the blood supply and the surrounding immune cells." (PMID 40717228, 2025). "We found that protein expression of TTR and NF‐κB subsequently decreased, accompanied by a weakening of cancer cell invasion." (PMID 37688511, 2023). "Transthyretin is a liver-synthesized protein that is often used to evaluate the nutritional status of patients with malignant tumors." (PMID 36960201, 2023). "The urine proteome profile of PCa and cancer-free subjects was analyzed by two software packages and 18 dysregulated proteins, of which 5 (TTR, EFEMP1, CDH1, SECTM1, KLK3) common to both software, were found." (PMID 35454907, 2022). "Another panel constituting of CA-125, ApoA1, TTR, and H418, was able to differentiate OC patients at early stage of disease from cancer-free healthy control samples with 74% sensitivity at 97% specificity." (PMID 31608277, 2019). "With the stability and accuracy, we can find Her-ELISA, PDGF-AA, Prolactin and TTR is the best biomarkers for classifying cancer samples from healthy to cancer data." (PMID 30396341, 2018). "We find the combination which contains TTR and Prolactin gives high performance for cancer detection." (PMID 30396341, 2018). "The three peaks for which proteins were identified, Serum Amyloid A, transthyretin and apolipoprotein A-I are consistent with data from a variety of other cancers." (PMID 22294182, 2012). "Within the cancer group, increased levels of CRP (cut-off > 40 mg/ml) in serum were associated with lower levels of TTR (p = 0.08) and RBP (p < 0.05)." (PMID 16225703, 2005). "Absolute levels of TTR as well as RBP in serum are negatively affected by the disease and by inflammatory processes associated with the cancer." (PMID 16225703, 2005). "As depletion of nutritional reserves and a subsequent significant weight loss can lead to an increased risk of morbidity, reduced chemotherapy response, and shorter survival in patients with cancer, TTR is a valid prognostic marker." (PMID 16225703, 2005). "In women with cancer, serum levels of both TTR and RBP were lower compared to healthy controls (p < 0.01)." (PMID 16225703, 2005). "Results show that, although the microheterogeneity of TTR itself and the occurrence of possible immunoreactive fragments thereof in serum and ascites fluid is unaffected by the cancer." (PMID 16225703, 2005). "On the other hand, when the differing inflammatory statuses were considered, obvious differences were observed between the cancer patients for serum levels of TTR and RBP." (PMID 16225703, 2005). "Emerging evidence suggests that low serum TTR levels are associated with poor nutritional status and increased systemic inflammation, both of which are negative prognostic indicators in cancer patients undergoing chemotherapy." (PMID 40559081, 2025). "However, other studies point to the involvement of TTR in intracellular processes that contribute to cancer progression." (PMID 40717228, 2025). "However, the addition of recombinant TTR enhanced the invasive ability of cancer cells instead, accompanied by elevated NF‐κB, p‐AKT, and p‐ERK protein expression." (PMID 37688511, 2023).
cancer (continued). "As the level of TTR declines during the progression of PC, TTR might originate from somewhere other than the cancer." (PMID 29190982, 2017). "Actin, transthyretin, lamin a/c, fibrinogen and apolipoprotein A-I are all proteins identified in one or more of the mentioned studies, and several of these proteins have been connected to cancer or used as cancer markers." (PMID 21711556, 2011). "Transthyretin (also known as thyroxin-binding prealbumin) has also been reported as a marker, decreased for ovarian and increased for lung cancer." (PMID 20551956, 2010). "Therefore, TTR might rapidly reflect the nutritional status and systemic inflammation, and low TTR levels was an indicator of poor prognosis among cancer patients in palliative care settings." (PMID 33808957, 2021). "The mechanism by which TTR is reduced in cancer is still unknown." (PMID 24586698, 2014). "A comprehensive cancer detection tool employing established biomarkers (ApoA1, CA125, CA19-9, CEA, ApoA2, and TTR) has demonstrated promise in predicting multiple cancers at a reasonable cost." (PMID 38540782, 2024). "LRG1 has also been evaluated in plasma alongside TTR and CA19-9, where this panel exceeded the accuracy of CA19-9 alone by over 10% in its ability to discriminate PDAC from benign controls and other cancers." (PMID 36969742, 2022). "Protective mechanisms included defense against infection (Alpha-1-B glycoprotein A1BG, Serpin family A member 1 SERPINA1, Transthyretin TTR), neuroprotection (TTR), and reduced risks of inflammation, infections, and cancer (SERPINA1, Keratin 10 KRT10)." (PMID 36145440, 2022). "The final panel proteins (LRG1, TTR, and CA19-9) were tested on 1002 samples—composed of normal, benign, other cancers, and PDAC—which were divided into training (n=684) and test sets (n=318) at a 4:1 ratio." (PMID 29190982, 2017). "Several urine biomarkers relevant to cancer research including HE4, OPN, CA 125 and TTR were examined using WB in order to confirm their presence in urine." (PMID 23723977, 2013). "On the other hand, myosin regulatory light chain 2, galectin-1, lipid-binding AI, annexin V, transthyretin, CARD-inhibitor of NF-κB-activating ligand, and actin prepeptide were downregulated in cancer samples." (PMID 23374291, 2013). "Another multivariate test used in the diagnosis of OC to evaluate the risk index for malignancy is the OVA1 assay, which is composed of five cancer-related proteins: CA125, ApoA-1 (apolipoprotein A-1), TTR (transthyretin), TF (transferrin), and β2-microglobulin." (PMID 38732363, 2024). "It should also be noted that TTR and KNG1 were also expressed and suppressed in other types of cancer, while AHSG and F2 were only expressed in CCA and liver hepatocellular carcinoma and only suppressed in CCA, which indicates that AHSG and F2 have higher specificity." (PMID 36224755, 2022). "The four-biomarker panel with HE4, creatinine, CEA, and TTR was found to be the most useful for the classification of cancer compared with that of benign tumors regardless of disease status." (PMID 31590408, 2019). "Interestingly, TTR showed the highest performance in early-stage cancers, whereas HE4 demonstrated the highest value in advanced-stage cancers." (PMID 31590408, 2019). "Subsequently, data, such as age, sex, presence or absence of metastasis, whether the cancer was initial or recurrent, serum albumin (Alb) and transthyretin (TTR) levels on admission, and survival time were examined." (PMID 40777143, 2025). "Moreover, malignant ovarian cysts contain many protein biomarkers that may be used for cancer detection, such as protein C inhibitor, apolipoprotein C-I and C-III, serum amyloid 4, and transthyretin." (PMID 32937851, 2020). "No TTR labelling however was seen within the epithelial cells of any cancer specimen." (PMID 16225703, 2005).
tumor (60 papers, 2005 to 2026). "The same TTR mutation was linked to neoplasms in European-descent individuals (EUR, fold-enrichment = 3.09, p = 0.003)." (PMID 38523305, 2024). "Whilst we observe a broadly comparable proteome relative to the human non-diseased brain, we identify cytoplasmic proteins α-trypsin, actin, apolipoprotein A1 and transthyretin which may putatively be associated with the GBM infiltrative tumour margin." (PMID 40617935, 2025). "Besides APP and APLP, another amyloidogenic protein such as α-synuclein (SNCA) and transthyretin (TTR) is reported to an association with tumorigenesis and tumor growth." (PMID 34066808, 2021). "This detailed analysis of treatment pathways confirms the highly complex medical care and the need for close multidisciplinary collaboration when treating patients who develop TTR-HO following tumor/ treatment." (PMID 39814823, 2025). "The management of patients with TTR-HO requires frequent inpatient and outpatient visits for tumor follow-up and management of incident comorbidities, and most patients with TTR-HO require intense polytherapy." (PMID 39814823, 2025). "Although it is difficult to disentangle the medical burden of TTR-HO from the general burden of tumor survivorship, we provide important detail on the pathways of patients who develop TTR-HO following tumor treatment." (PMID 39814823, 2025). "The goal of this study was to investigate the utility of a transthyretin binder (TB-01) to achieve high tumor uptake of the resultant PSMA radioligand." (PMID 38610940, 2024). "Aside from the improved in vivo half-life, previous studies have highlighted the potential use of a transthyretin-binder for the delivery of hydrophobic cytotoxic drugs to tumor tissue." (PMID 38610940, 2024). "At the same time, TTR acts as a cytokine to influence the differentiation function of bone marrow cells and plays a role in the tumor microenvironment." (PMID 37688511, 2023). "From the previous study of our group, the dysregulated proteins AMBP, KLK3, LMAN2, and TTR were found dysregulated in urine and tumor tissue from PCa patients, while SECTM1 was only found in urine from PCa patients, and CDH1 and EFEMP1 were only in PCa tissue." (PMID 35454907, 2022). "TTR also participates in many other biological functions that are directly or indirectly dedicated to tumor progression." (PMID 34603388, 2021). "Whereas our method yielded a significant P value of 0.001 for separating NSCLC tumor patients with different TTR, implying that it classifies samples into biologically relevant subgroups." (PMID 20569491, 2010). "Like apolipoprotein A-1, transthyretin was in the panel for the xenograft vs non-tumour-bearing mice as well as for epirubicin or cisplatin treated vs untreated xenografts." (PMID 20551956, 2010). "The Cox multivariable analysis underscored the significance of TTR and various clinicopathological factors, encompassing age, tumor location, R0 resection status, differentiation grade, disease stage, postoperative chemoradiotherapy, and preoperative CEA levels, as substantial prognostic indicators." (PMID 39975596, 2025). "Although it is challenging to isolate the burden of TTR-HO from the general medical burden following tumor and treatment, TTR-HO is a distinct indication with unique challenges for those who experience rapid and persistent weight gain resulting from hypothalamic damage." (PMID 39814823, 2025). "The downregulation of TTR in the IDH mutation group may be linked to lower uptake of thyroid hormone, which causes a favorable prognosis through repression of tumor cell growth or differentiation." (PMID 41007824, 2025). "We refer to the development of HO following tumor/treatment as TTR-HO." (PMID 39814823, 2025). "This example may pave the way for future applications of this transthyretin binder in conjunction with other tumor-targeting agents, in particular when hydrophilic properties would be desirable." (PMID 38610940, 2024).